SMURF2 (SMAD specific E3 ubiquitin protein ligase 2)
Diseases named in the same sentence as SMURF2 in open-access papers (continued):
Sharing a sentence is not in itself a finding about the gene and the disease.
cancer (continued). "In summary, our current findings indicate that FFLZ is a potential therapeutic or dietary supplemental agent for cancer patients and that it functions via the caveolin-1/Smad7/Smurf2-dependent ubiquitin-mediated degradation of TGFR." (PMID 27830743, 2016). "In contrast, there have been several reports demonstrating decreased expression of Smurf2 in other types of cancer." (PMID 24485087, 2014). "Levels of Smurf2 protein in ER+/PR + cancer cells (MCF-7 and T47D) and those in HER2+/ER+/PR + BT474 cells and HER2+/ER-/PR- SK-BR-3 cells were comparable with Smurf2 levels in MCF-10A cells." (PMID 24485087, 2014). "On the other hand, several researchers have reported that TGFβ increases sensitivity to cisplatin for cancer treatment and therefore, SMURF2 will be available as a biomarker for identification of responders for FOLFOX therapy." (PMID 22095227, 2012). "A novel, cancer-fighting function was recently discovered for Smad ubiquitination regulatory factor 2 (Smurf2)." (PMID 22429979, 2012). "This new cancer fighter, Smurf2, was originally identified as Smad ubiquitination regulatory factor 2, which is an E3 ubiquitin ligase involved in the signaling control of the TGF-β and BMP super-family of poly-peptide growth factors." (PMID 22429979, 2012). "The Smurf2 and Smad7 complex ubiquitinates TβRI, a key event resulting in degradation of the receptor and TGFβ resistance in cancer cells." (PMID 14562029, 2003). "In addition, resistance to existing cancer therapy related to SMURF2 and sensitivity mechanisms is discussed." (PMID 41683957, 2026). "SMURF2 is an E3 ligase that is differentially expressed in multiple cancer types." (PMID 41683957, 2026). "Recent findings shed light on the intricate involvement of SMURF2 in cancer progression." (PMID 39697237, 2024). "However, in specific cancer subtypes, SMURF2’s activity promotes oncogenic pathways, such as the Wnt/β-catenin signaling pathway." (PMID 39697237, 2024). "The emerging evidence on the role of SMURF2 in modulating ferroptosis by mediating the degradation of glutathione S-transferase P1 (GSTP1) dismantles a key defense against ferroptosis, thereby predisposing cancer cells to this unique form of cell death." (PMID 39697237, 2024). "SMURF2 promotes ferroptosis in cancer cells by mediating the degradation of GSTP1." (PMID 39697237, 2024). "Loss of SMURF2 stabilizes RACK1, promoting cancer cell survival and proliferation." (PMID 39697237, 2024). "The SMURF2-mediated degradation of HIF1α could present a therapeutic avenue to disrupt cancer cells’ adaptive mechanisms, thereby mitigating treatment resistance." (PMID 39697237, 2024). "Such combination therapies may improve outcomes in cancers where SMURF2-mediated degradation of HIF1α is a key factor in therapeutic success." (PMID 39697237, 2024). "Enhancing SMURF2 activity could be particularly beneficial in cancers resistant to current treatments, especially those driven by hypoxia." (PMID 39697237, 2024). "Together, these findings suggest that CDK4/6 inhibitors may synergize with SMURF2’s role in degrading HIF1α, presenting a promising combination strategy to target hypoxic pathways in cancer therapy." (PMID 39697237, 2024). "Targeting the SMURF2-HIF1α axis to modulate the degradation of critical proteins involved in therapeutic resistance could enhance cancer cells’ sensitivity to targeted therapies, offering a promising strategy to counteract these resistance mechanisms." (PMID 39697237, 2024). "Thus, Targeting the SMURF2-HIF1α axis represents a novel approach to counteracting the adaptive mechanisms cancer cells employ within the TME." (PMID 39697237, 2024). "SMURF2 has multiple roles that demonstrate its importance in cancer pathophysiology." (PMID 39697237, 2024). "The interplay between SMURF2 and HIF1α represents a promising avenue for cancer therapy." (PMID 39697237, 2024).
cancer (continued). "Importantly, miRNA-195 and miRNA-497 effectively targeted SMURF2 and increased TβRI levels in TGFβ1-treated cancer cells." (PMID 37568787, 2023). "In addition, the survival plot of relationship between Smurf2 and cancer prognosis in different types of cancers was shown." (PMID 37291499, 2023). "miR-15b overexpression promoted EMT through the suppression of SMURF2 in BxPC-3 cancer cells." (PMID 37568787, 2023). "Smad ubiquitination regulatory factor 2 (Smurf2) plays various roles in cancer progression." (PMID 35361871, 2022). "The mechanism(s) underlying shorter TSF in patients with low Smurf2 expression may include the involvement of Smurf2 in the stem cell-like properties of cancer cells." (PMID 35361871, 2022). "However, the role of Smurf2 in the DNA damage response in tumors and how it interacts with cancer therapies, such as chemotherapy and radiation, are unclear." (PMID 35710591, 2022). "However, it has been increasingly realized that Smurf2 modulates pleomorphic pathways in different cancers." (PMID 35710591, 2022). "Accordingly, the role of Smurf2 in cancer biology seems to be “context-dependent”." (PMID 35361871, 2022). "Smurf2 was predominantly expressed in the cytoplasm of cancer cells in primary tumors." (PMID 35361871, 2022). "Therefore, the treatment of cancers with etoposide is accomplished, in part, through the destabilization of the genome in a pS384 SMURF2-dependent manner." (PMID 35327659, 2022). "Smurf2 was predominantly expressed in the cytoplasm of cancer cells in liver metastases." (PMID 35361871, 2022). "Considering the elevated expression of SMURF1, SMURF2, NEDD4-2 in different cancers (Section 7.1 and Section 7.3), similar inhibitors of SMURF2 and NEDD4-2 could be identified." (PMID 33418880, 2021). "In lung cancer, SMURF2 was shown to play a cancer-promoting role by ubiquitinating TβR1." (PMID 33418880, 2021). "We hypothesized that SMURF2 might have a distinct molecular biodistribution in cancer versus normal cells and tissues." (PMID 31003445, 2019). "Investigations of the mechanistic aspects associated with the distorted distribution of SMURF2 in human cancer showed that such an alteration does not involve the CRM1-mediated nuclear export." (PMID 31003445, 2019). "In addition, these proteins are prevalent in multiple human cancers, implying an intriguing possibility that SMURF2 stability and localization are coordinated by 14-3-3s." (PMID 31003445, 2019). "This difference might have been the result of the different roles of TGF‐β1 and SMURF2 in late‐stage cancer." (PMID 31581360, 2019). "Interestingly, although SMURF2 protein levels were significantly elevated in BRCA tumors, analysis of the TCGA RNA-Seq data showed a strong decrease in mRNA expression of SMURF2 in cancer versus normal tissues." (PMID 31003445, 2019). "Interestingly, the authors also showed that Smurf2 promotes mesenchymal-epithelial transition (MET), and that its expression levels are negatively associated with cancer cell resistance to gemcitabine treatment." (PMID 30116722, 2018). "However, when PR was moderate/intense, only 24.19 and 29.03% of malignant tumors showed moderate/intense expression of Smurf2 and CNKSR2." (PMID 29534682, 2018). "To determine the relationship between Smurf2 and A‐type lamins in human tissues, we obtained a collection of human normal and cancer tissues (tissue microarrays—TMAs) from US Biomax and stained these tissues with IHC‐specific anti‐Smurf2 and antilamin A/C antibodies." (PMID 29405587, 2018). "Our studies have shown that when ER was no/mild, 61.29 and 58.06% of malignant tumors showed moderate/intense expression of Smurf2 and CNKSR2, while only 29.03% of malignant tumors showed moderate/intense expression of Smurf2 and CNKSR2 when ER was moderate/intense." (PMID 29534682, 2018).
cancer (continued). "It has been reported that Smurf2 together with the E2 ubiquitin-conjugating enzyme UBCH5, stabilize the KRAS oncoprotein, the most frequently mutated transforming oncogene in human cancers." (PMID 30116722, 2018). "Additionally, the expression levels of Smurf2 were reported to be significantly elevated in several types of cancers including esophageal squamous cell carcinoma tumors and chemo-refractory tumors such as recurrent hepatocellular carcinomas." (PMID 30116722, 2018). "Furthermore, we demonstrate that the reciprocal relationship between Smurf2 and A‐lamins is preserved in different types of mouse and human normal and cancer tissues." (PMID 29405587, 2018). "Finally, the data obtained in IHC studies of tissues from Smurf2‐deficient and wild‐type mice, as well as on tissue microarrays incorporating more than 460 human normal and cancer tissues, provided additional support for Smurf2 as a regulator of A‐lamins." (PMID 29405587, 2018). "Smurf2-deficiency may also result in impaired mitotic regulation and subsequent genomic instability, as demonstrated in several human cancer cell lines with siRNA-mediated silencing of Smurf2." (PMID 24485087, 2014). "However, no inactivating mutation of SMURF2 has been reported in human, and information about Smurf2 expression in human cancer remains limited or complicated." (PMID 24485087, 2014). "The involvement of Smurf2 in cancer development has been controversial." (PMID 24485087, 2014). "To understand whether LATS1 stability is also regulated by other members of the NEDD4-like family of E3 ligases, we selected 4 ubiquitin ligases including NEDD4, WWP1, Smurf1 and Smurf2 that have been shown to be involved in the development of human cancers." (PMID 23573293, 2013). "This insight into the SMURF2-GSTP1 interaction adds a crucial layer to our understanding of ferroptosis regulation, presenting SMURF2 as a key facilitator of this iron-dependent form of cell death, which could be leveraged to enhance the efficacy of pro-ferroptosis cancer therapies." (PMID 39697237, 2024). "Thus, SMURF2 emerges as a cornerstone in cancer therapeutics." (PMID 39697237, 2024). "Similarly, the E3 ligase SMURF2 has been identified to promote ChREBP ubiquitination and degradation via the proteasome pathway and thereby influence aerobic glycolysis, oxygen consumption, and cell proliferation in cancer cells." (PMID 37937648, 2023). "Additional influence on the accumulation of SMURF2 in the cytoplasm of cancer cells might be ascribed to the altered activities of protein kinases, in particular of serine/threonine kinases, which are known to facilitate the binding of 14-3-3 proteins to their substrates." (PMID 31003445, 2019). "Thus, the role of the Smurf2/SCFβ−TrCP module in cancer may vary considerably depending on the cell type and molecular composition, and should be determined in a particular context." (PMID 30116722, 2018). "Conversely, in certain cancer contexts, curcumin promotes pyroptosis by stabilizing NLRP3 through the inhibition of Smurf2-mediated ubiquitination." (PMID 40806716, 2025). "•PIK3CA and GATA3 were the main cancer driver genes in luminal samples, and candidate drivers were GRHL2 and SMURF2." (PMID 39208653, 2024). "In luminal samples, PIK3CA and GATA3 were the main cancer drivers, and other drivers were GRHL2 and SMURF2." (PMID 39208653, 2024). "In contrast, luminal cancers show less consistent up-regulation of SCRIB and VANGL2 mRNAs and rare up-regulation of SMURF2 or WNT11." (PMID 36675340, 2023). "Combined with our results indicating that Smurf2 inhibition can also sensitize cells to the cytotoxic effects of cisplatin-based chemotherapy and radiation, these previous results indicate that Smurf2 may act as a common modulator of resistance to diverse cytotoxic cancer therapies." (PMID 35710591, 2022).
cancer (continued). "Since the identification of Smurf2, its various roles have been explored not only as a regulator of TGF-β but also as a direct regulator of the cell cycle and cancer development." (PMID 35361871, 2022). "We further demonstrated that this phenomenon is relied on unaltered E3 ubiquitin ligase activity of SMURF2, leading to the stabilization of KAP1 in cancer cells." (PMID 35406379, 2022). "This likely occurs in cancers when a high TGFβ signal disrupts Nur77-mediated ID1 interaction with and ubiquitylation by Smurf2." (PMID 33990575, 2021). "By contrast, in aggressive stages of cancer, for example, in triple negative breast cancer, the SMURF1 level was shown to neutralize the SMURF2 inhibitory effect of tumorigenesis." (PMID 33418880, 2021). "An inverse correlation between SMURF2 expression and phosphor-SMAD2 levels has also been observed in cancers." (PMID 33418880, 2021). "We discovered a novel mechanism of regulation of HIF-1α, involving Smurf2 E3 ubiquitin ligase, in CDK4/6 inhibitor treated cancer cells where HIF-1α is destabilized." (PMID 34611473, 2021). "Interestingly, results obtained in CHX studies indicated that the cytoplasmic SMURF2 is considerably more stable than its nuclear counterpart in both cancerous and non-cancerous cell models, though the ratio between the cytoplasmic and nuclear pools of SMURF2 was higher in cancer cells." (PMID 31003445, 2019). "One possible approach is to examine these effects in SMURF2 genetically-ablated MDA-MB-231 cells, as well as in other human cancer cell models." (PMID 30116722, 2018). "In this review, we highlighted and discussed the cancer related biological functions of two C2-WW-HECT E3 ligases, Smurf1 and Smurf2." (PMID 30116722, 2018). "We also observed that Smurf2 expression was decreased in MCF10A cells however, a strong up-regulation was observed in MDA-MB-231 cells compared to other cancer cell lines." (PMID 25191523, 2014). "Finally, in the context of cancer, curcumin has been shown to induce NLRP3-dependent pyroptosis by targeting Smurf2, an E3 ubiquitin ligase that mediates NLRP3 degradation." (PMID 40806716, 2025). "Investigating the regulatory relationship between SMURF2 and HIF1 could provide new insights into targeting the metabolic vulnerabilities of cancer cells." (PMID 39697237, 2024). "Investigating other SMURF2 targets and interactions with GSTP1 within the TME, especially involving immune cells, could further elucidate its role in cancer survival and unveil new immunotherapeutic opportunities." (PMID 39697237, 2024). "Furthermore, this review aims to elucidate the intricate interplay between HIF1α, SMURF2, and the TME, shedding light on their significance in shaping tumorigenesis and cancer progression." (PMID 39697237, 2024). "Additionally, SMURF2 modulates the stability and function of proteins like KAP1 in cancer cells and targets TGF-β receptors for degradation, impacting cancer cell behavior and TGF-β signaling." (PMID 39697237, 2024). "Previous studies have revealed that the Smurf2 E3 ubiquitin ligase may induce CNKSR2 in cancer cells and participate in cancer cell proliferation." (PMID 38169557, 2024). "Various studies have reported that miR‐503 can target SMURF1 and SMURF2 (SMAD ubiquitination regulation factors 1 and 2), thereby enhancing TGF‐β (transforming growth factor beta) signaling in individual biological processes other than cancer." (PMID 37212485, 2023). "A systematic search in different electronic databases indicated that, among HECT-type E3 ligases, members of the NEDD4 family including NEDD4-1, NEDD4L, SMURF-1, SMURF-2, WWP1, WWP2, and ITCH have been investigated in many various cancers with defective autophagy, as reviewed in next sections." (PMID 36918822, 2023). "Components of the ubiquitination system, such as Smurf2, have not yet been utilized or explored for targeted cancer therapy in the form of chimeric proteins, thus represent a novel approach to cancer treatment." (PMID 36612252, 2022).
cancer (continued). "Although the E3 ubiquitin ligase Smurf2 is reported to target and degrade YY1 protein in several cancers, unfortunately, we did not obtain positive evidence of Smurf2 on YY1 in TNBC." (PMID 35383155, 2022). "The data that we present in this study show that SMURF2 directly binds, ubiquitinates, and regulates the protein abundance of KAP1 in E3 ligase and cell-context-dependent manners, which is also evident in certain mouse and human normal and cancer tissues." (PMID 35406379, 2022). "Further we analyzed the association between Smurf2, CNKSR2, ER, PR, and HER2 expression with non-malignant and malignant tumors using multiple logistic regression analysis taking non-malignant tumors as the reference." (PMID 29534682, 2018). "Overall, the expression pattern of Smurf2 and CNKSR2 showed a significant positive association (P < 0.001) between each other among non-malignant and malignant tumors." (PMID 29534682, 2018). "According to the adjusted Odds ratio, malignant tumors were 25.94 times more likely to exhibit moderate/intense expression of Smurf2, taking non-malignant tumor as the reference (OR = 25.94, 95%CI: 3.86–174.06)." (PMID 29534682, 2018). "Interestingly, among malignant tumors, 51 out of 62 cases (82.26%) showed moderate/intense expression of CNKSR2 when Smurf2 expression was moderate/intense." (PMID 29534682, 2018). "Only 5 out of 62 malignant tumors (8.06%) showed a no/mild expression of CNKSR2 when Smurf2 expression was moderate/intense." (PMID 29534682, 2018). "Initially, Smurf2 has been found to play an important role in cellular transformation by regulating the TGF-β/BMP signaling, deregulation of which will invariably lead to developmental defects and/or diseases, including cancer." (PMID 25191523, 2014). "Both Smurf2 and NEDD9 are overexpressed in multiple types of cancers." (PMID 20825672, 2010). "It will be important to determine whether Smurf2 and NEDD9 levels correlate with each other in human cancers." (PMID 20825672, 2010). "By targeting SMURF2 to modulate HIF1α stability, it may be possible to influence hypoxia-related cancer pathways without directly inhibiting HIF1α itself, presenting a novel therapeutic approach." (PMID 39697237, 2024). "Notably, SMURF2’s ability to promote ferroptotic cell death through GSTP1 degradation offers an alternative pathway to overcome apoptosis resistance, expanding therapeutic options for refractory cancers." (PMID 39697237, 2024). "Besides, some NEDD4 E3 ligase family genes might affect the prognosis regarding different cancer types to different extents such as WWP2 and Smurf2." (PMID 37291499, 2023). "Most of the cancer tissues showed either a lower expression of SMURF2 and higher expression of KAP1 or the opposite: a higher expression of SMURF2 and lower expression of KAP1, suggesting that the carcinogenic process may change the relationship between the expression of these proteins." (PMID 35406379, 2022). "Our in vitro data demonstrate that Smurf2 knockdown significantly accelerated cancer cell migration, but not cell proliferation or invasion; the reasons for the latter remain unclear." (PMID 35361871, 2022). "Notably, the expression levels of SMURF2, quantified in IHCs as SMURF2 staining intensity, were comparable between normal and PRAD samples, though some reduction in the percentage of SMURF2-positive cells was recorded in cancer." (PMID 31003445, 2019). "Remarkably, recent studies showed that SMURF2 could be phosphorylated by AKT and ERK5, two pro-tumorigenic serine/threonine kinases which expression and/or activities are upregulated in many cancers." (PMID 31003445, 2019).